C3 (complement C3)
Diseases named in the same sentence as C3 in open-access papers (continued):
Sharing a sentence is not in itself a finding about the gene and the disease.
infection (continued). "Interestingly, cell studies have revealed that intracellular C3 activation is basal during infection with RSV, an enveloped virus." (PMID 38368584, 2024). "The highest levels of C3 mRNA were observed on the 20th and 30th days following infection." (PMID 39766497, 2024). "However, a thorough investigation of the underlying mechanism and potential compensatory pathways is warranted as well as the effect of C1q loss or inhibition as it appears to play a larger role in these infection than C3 and C5." (PMID 38881889, 2024). "Thus, the GlyperATM formulation significantly shielded epithelial integrity, successfully blocked infection with Omicron and release of viral particles, and decreased intracellular complement C3 activation within human airway epithelial cell cultures." (PMID 36949547, 2023). "The most responsive C3 genes in our infection model were c3a." (PMID 36622851, 2023). "Of note, only HT saliva samples could reduce the inflammatory C3 expression in addition to the reduced infection (green signal)." (PMID 37551989, 2023). "We observed that Delta readily penetrated deep into the respiratory epithelium and this was associated with major tissue destruction, high LDH activity, high viral loads and pronounced innate immune activation as observed by intrinsic C3 activation and IL-6 release at infection sites." (PMID 37915577, 2023). "However, liver damage was more severe in C3-/- than in wt mice 48 hrs after MHV-3 infection, a finding confirmed by the higher serum ALT concentration in C3-/- mice 48 hrs after MHV-3 challenge." (PMID 35573780, 2022). "Depletion of complement components C3 and C5 in the juvenile rats with cobra venom factor prior to infection restores full virulence of unencapsulated mutants, demonstrating the importance of resisting complement for virulence in the rat infection model." (PMID 36304526, 2022). "Additionally, C3−/−, factor B−/−, and C4−/− mice lost less weight over the course of infection than wild type mice." (PMID 35955740, 2022). "Interestingly, a significantly larger proportion of C3-KO cells harbor only cytosolic bacteria at 4 h post-infection compared to C3-expressing cells (WT, ∆AUG1, and ∆2–25) and contain significantly more cytosolic bacteria." (PMID 35546365, 2022). "Moreover, the role of C3 and C3aR in regulation of apoptosis are supported by C3aR KO mice showing aggravated liver apoptosis compared to WT mice after infection with the intracellular invading bacteria Listeria monocytogenes." (PMID 35432387, 2022). "Plasma IL-1β and C3 were quantified 0, 2, 4, 8, 12, 16, 24, 48, and 96 h post-infection." (PMID 36026499, 2022). "A local downregulation of c3 expression has also been described in other monogenean infections." (PMID 36088326, 2022). "Analysis of the serum of WT, C3-/- and C5aR1-/- mice infected with conidia showed that, although not at statistically different levels in different groups, the anaphylatoxin C5a was indeed generated during infection." (PMID 36211424, 2022). "Serum concentrations of TNF-α, IL-6, and IFN-γ were higher in C3-/- than in wt mice 24 and 48 hrs after infection (–E), indicating that mice genetically deficient in C3 may experience more severe liver damage due to the greater replication of viral load." (PMID 35573780, 2022). "Two genes (c3 and tgfb) were significantly reduced by infection in both light conditions." (PMID 34782020, 2021). "C3-/- / Daf-/- and C3-/- mice had a similar bodyweight loss upon PR8-HK4 infection." (PMID 34197564, 2021). "Unlike the C3 deficient mice, iNOS−/− mice eventually succumb to infection, largely the result of their inability to control parasite proliferation." (PMID 33692968, 2021). "Finally, we assessed the contribution of complement in PTX3-mediated activity in K. pneumoniae infection, by comparing the survival of wild-type and Ptx3-/- mice to C3-/- and Ptx3-/-/C3-/- mice after intranasal infection." (PMID 34093560, 2021).
infection (continued). "Additional studies comparing WT and C3 KO mice demonstrate a trend towardsincreased synaptic number in C3 KO mice compared to WT which supports our hypothesis thatcomplement is responsible for pathologic synaptic pruning in S. epidermidisshunt infection." (PMID 34612709, 2021). "As a control, we also infected WT and C3 deficient animals with 25 tachyzoites of the Type I RH strain intraperitoneally to demonstrate that C3 is protective during infection regardless of parasite genotype." (PMID 33692968, 2021). "Further experiments determining whether avian gC proteins bind and inhibit C3 is warranted to address these differences and the potential role gC and complement may play during natural infection in the host." (PMID 34452285, 2021). "Therefore, we stained urinary sediment for C3a/C3 expression obtained from 12 patients with serious infections." (PMID 34767613, 2021). "Remarkably, C3, central player in the complement cascade, has been found within the mucus barrier, which elucidates complement role in early immune response upon pathogen infection in the airways." (PMID 34197564, 2021). "infections with avian-strains in man might partially depend on the individual levels of C3, or of other factors participating in the activation or effector pathways of the complement cascade." (PMID 33767691, 2021). "The complement system is the first line of the innate immune system, which detects virus-infected cells at early stages and lyses them to prevent further infection, and coagulation factors can boost the complement system through the cleavage of C3 and C5, resulting in activation." (PMID 33271804, 2020). "The effect of M marinum after IP and mucosal infection showed common overrepresented (e.g., ribosomal proteins, lysine-tRNA ligase, and leukotriene A4 hydrolase LTA4H) and underrepresented (e.g., complement components including C3, annexin, and tropomyosin alpha-1) proteins in response to infection." (PMID 32344637, 2020). "Complement C3 becomes activated via activation pathways during infection." (PMID 30931168, 2019). "Moreover, C3 activation has been reported in the cornea soon after infection with herpes simplex virus type 1 (HSV-1), which is a common cause of corneal sensory nerve damage in patients." (PMID 31414985, 2019). "As the infection progresses increased presence of C3 in plasma, coming from the liver or from dysregulated platelets, may overwhelm its beneficial effect." (PMID 30992428, 2019). "However, age at disease onset, infection status, presence of embolism, and levels of IgA, IgM, C3, and blood urea nitrogen (BUN) were comparable among the three groups." (PMID 31057017, 2019). "C3-deficient mice are more susceptible to infection with C. albicans due to impaired fungal clearance without affecting inflammatory responses." (PMID 30934602, 2019). "Infection of mice lacking C3 generates phenotypes associated with loss of anaphylatoxin signaling, including decreased cytokine production, decreased IgG secretion, and a reduced proliferation of lymphocytes in the spleen." (PMID 29581196, 2018). "C3–/– mice exhibited more airspace inflammation, including eosinophils, at 2 dpi than their wild-type controls, although this relationship was reversed later in infection." (PMID 30301856, 2018). "In contrast, all 10 C3−/− animals succumbed to the infection at days 5 to 6 postinfection." (PMID 29581196, 2018). "In contrast, the C3–/– mice were significantly protected from infection, with no significant weight loss evident at any time point." (PMID 30301856, 2018). "However, antibody-mediated protection is dependent on a functional complement system because anti-R. australis-treated C3−/− mice were unable to successfully combat the infection (green line)." (PMID 29581196, 2018).
infection (continued). "For example, ligation of CR3 by the surface virulent factor BAD1 of Blastomycetes dermatitidis results in TNF suppression and immune invasion, and infection of murine macrophages with Mycobacterium avium in C3-depleted medium resulted in a significantly higher level of TNF production." (PMID 29632532, 2018). "By comparing infection of MDM with SCHU S4 in C3-depleted and C3-replenished human serum, the investigators found that the presence of C3-opsonization decreased the phosphorylation of MAP kinases ERK and p38 and decreased levels of secreted TNF, IL-6 and IL-1β." (PMID 29312899, 2017). "Secondary infection with C3-opsonized wild type SCHU S4 resulted in macrophage death." (PMID 29312899, 2017). "Although the role of the protein product of C3 (C3a) on neutrophils remains controversial, it has been previously reported that mice lacking C3 exhibit less neutrophil infiltration in brain injury and infection models." (PMID 29126429, 2017). "In comparing the groups with and without infection, the SNPs most significantly associated with infection were located in complement genes, including C3, C5, C6, C7, C9 and MBL2 (P < 10−6)." (PMID 27063552, 2016). "C3 plays a key role in the activation of the complement system, and C5a is crucial in the downstream functions of the complement cascade, which can recruit phagocytic cells to the infection sites." (PMID 27515123, 2016). "Additionally, most strains produce chemotaxis inhibitory protein that can delay leukocyte migration toward the site of infection and secrete various C3 complement inhibitors." (PMID 26340099, 2015). "Univariate linear regression between C3 and coagulation and infection." (PMID 23091606, 2012). "Similarly, the induction and expansion of CD8+ T cells during infection with lymphocytic choriomeningitis virus (LCMV) depended on C3." (PMID 20442876, 2010). "Upon infection of C3-deficient mice with influenza virus, a significant impairment in priming of CD4+ helper cells and virus-specific cytotoxic T lymphocytes was observed, which resulted in delayed clearance of the infection and increased viral titers." (PMID 20442876, 2010). "Thus C3 was important for the infection of DCs in vivo, and for their ability to present antigen to CD8+ T cells." (PMID 20442876, 2010). "However, the use of heterologous viruses in CAP88 clearly showed that the anti-C3 response was maintained, albeit at lower levels (declining from a peak of >1∶3,000 to stabilize at approximately 1∶700 during the second year of infection)." (PMID 19763271, 2009). "In order to determine whether the lower levels of C3 were indeed the result of high levels of complement system activity during infection, the C3 levels of the DHF patients were also measured during the convalescent phase." (PMID 19707565, 2009). "The C3−/− mice also showed increased morbidity over the course of the infection." (PMID 19112490, 2008). "Many forms of infection or tissue injury lead to activation of the complement system resulting in the cleavage of complement components C3 and C5 and generation of the anaphylatoxins C3a and C5a." (PMID 18559098, 2008). "Also, complement component 3 (C3) and the antibody-mediated phagocytosis by Kupffer cells have been identified as the remaining factors required for intravascular clearance of African trypanosomes during early infection." (PMID 40986119, 2025). "Previous reports revealed that the C3 protein enhances TbCSV replication, prompting us to investigate whether the decreased accumulation of TbCSVdC3 can be attributed to the impaired virus replication, using a local infection assay with minor modifications." (PMID 40025647, 2025). "However, this hypothesis must be weighed against the elevated infection reporting rates observed with C3 inhibitors." (PMID 40860872, 2025).
infection (continued). "Notably, the TP10 clinical trial in PGD showed no increase in infection risk following acute C3 inhibition, and recent clinical use of pegcetacoplan in kidney xenotransplantation helps to further assuage these concerns." (PMID 41031895, 2025). "Consequently, the majority of C3−/− mice succumbed to infection, in contrast to WT and C4−/− mice." (PMID 41279015, 2025). "However, except for α-SMA at 15 d.p.i., neither C3 deficiency nor LIC infection appeared to significantly alter these parameters." (PMID 41251377, 2025). "However, while some reports have shown expression of C3 in airway epithelial cells and highlighted its functional role in infection, less is known about the expression of C3a, C3aR, as well as C5, C5a and C5aR1 in the AE under steady-state conditions and in response to aeroallergens." (PMID 41148813, 2025). "Like C3, C5 loss did not impact bacterial abundance, with similar numbers of bacteria on catheters and in the surrounding brain tissue of both wild type and C5 KO animals over the course of infection." (PMID 38881889, 2024). "Furthermore, in conditions of C3 inhibition similar to those obtained with compstatin derivatives and pegcetacoplan, it has been observed that the low residual levels of C3 produced in local tissues can provide opsonic functions adequate for defense against infection." (PMID 39273426, 2024). "In the present study, we deposited C3 components on the surface of S. aureus by complement opsonization before cell infection and confirmed that C3-coatings remained on the surface of the bacteria after they have invaded the cells, suggesting S. aureus cannot escape or degrade C3 labeling." (PMID 39310788, 2024). "However, the contents of the important complement components, C3 and C4, which participate in the body's immune response through various complement activation pathways and contribute to early defense against infection, were substantially lower than those in the control group." (PMID 39296492, 2024). "However, C3b is key for bacteria opsonization and phagocytosis, and therapeutic strategies targeting C3 may hinder the normal in vivo response to infection." (PMID 37109229, 2023). "Thus, thoroughly assessing the hidden infection by not only bacterial cultures, but also histological staining for NAPlr and for plasmin activity, is critical in cases in which IF findings indicate C3-dominant glomerular deposition." (PMID 37176142, 2023). "Regarding sea turtles, complement proteins (C3, C4, C5) have been highlighted as a potential biomarker of C. caretta and C. mydas health when recovering in rehabilitation facilities as they serve as good indicators of stress, infection, or exposure to pollutants." (PMID 36830343, 2023). "We also found that C3-/- mice were not significantly more susceptible to infection with a sub-lethal dose of Hc, which contrasts with the increased susceptibility of C3-/- animals to challenge with opportunistic fungi, such as Candida albicans and Cryptococcus spp." (PMID 36174103, 2022). "gC can combine with glycosaminoglycans to promote the adsorption and infection of the virus, combine with blood factors to promote the spread and replication of the virus in the body, gC can also inhibit complement-mediated neutralization by binding to complement C3b." (PMID 36059553, 2022). "Infection of complement C1q and sIgM-deficient mice with S. mansoni as well as in vitro tests with sera from mice deficient in C3 and C4 revealed no major role for these soluble factors in vivo in regard to parasite maturation, fecundity and associated immunopathology." (PMID 33968028, 2021). "C3-mediated signaling could induce an antiviral state in previously uninfected cells, as the supernatant from complement-coated AdV infected cells was able to protect uninfected HeLa cells from infection with interferon-sensitive Sindbis virus." (PMID 32733480, 2020).
infection (continued). "In addition, PVB19 could be implicated in the activation of complement alternative pathway (CAP), since C3 level is often decreased in PVB19 infection with kidney involvement." (PMID 32646497, 2020). "While lower C3 levels could be caused by complement C3 deficiency, none of these patients showed increased susceptibility to infection, characteristic of the rare, genetic C3 deficiency." (PMID 31824513, 2019). "Infection of guinea pigs with A/Tiger/Harbin/01/2002 (H5N1) (HAB01), 2009 pandemic H1N1 A/Changchun/01/2009 (CH01) or a mouse-adapted A/Changchun/01/2009 H1N1 variant (MA CH01) resulted in increased concentrations of C3 in the serum when compared to uninfected controls." (PMID 28418930, 2017). "The significant accumulation of H2O2 in leaves of the SlERF.A1-, SlERF.A3-, SlERF.B4-, and SlERF.C3-silenced plants after infection of B. cinerea may suggest that the function of SlERF.A1, SlERF.A3, SlERF.B4, and SlERF.C3 in defense response against B. cinerea links to ROS generation." (PMID 28083004, 2016). "The interaction of VDBP with C5AR1 and C3 suggests that it has a role in inflammation, enhancing the chemotactic activity of complement 5a for neutrophils and activating macrophages, critical for the establishment of the early infection and subsequent propagation." (PMID 25276097, 2014). "Furthermore, the fluidic surfactant lining layer could also contribute to the recruitment of neutrophils to the site of infection by pro-inflammatory- and chemoattracting anaphylatoxin and C3a molecules that are cleaved from C3 molecules on the fungal surface." (PMID 25360787, 2014). "To determine whether reduced pulmonary C3 levels in the cirrhotic rats corresponded to reduced complement-mediated opsonization of pneumococci within their lungs, we quantified C3 deposition on pneumococci following infection." (PMID 17956621, 2007). "Infection with M. catarrhalis showed the same result and C3 ΔATG1 cells had a significantly higher IKK phosphorylation as compared to C3 KO cells." (PMID 41441980, 2025). "Through western blot analysis, we observed that EV-A71 infection resulted in the upregulation of GFAP, C3, and C5aR1 expression in a time-dependent manner." (PMID 39679722, 2025). "There were also differences in the slopes of the simple linear regression lines between other proteins (IL-18, C3, IL-10, and CD163) and time post infection that further highlighted the dissimilarity between Cov and nLongC immune recovery (Figure A1)." (PMID 41369364, 2025). "We aimed to investigate the role of C3 during chronic infection by L. interrogans strain FIOCRUZ L1-130 (LIC) in C57BL/6 wild-type (WT) and C3 knockout (C3KO) mice, monitored for 15, 30, 60, 90, or 180 days post-infection (d.p.i.)." (PMID 41251377, 2025). "At the cellular level, IVM imaging also confirmed the critical role of C3 and the C3 receptors in CRP-based KC capture of Sp23F at the high infection dose." (PMID 41214213, 2025). "C57BL/6 wild-type (WT) and C3 knockout (C3KO) mice were infected with 10 8 LIC and monitored at 15, 30, 60, 90 and 180 days' post-infection (d.p.i.)." (PMID 40236016, 2025). "Conversely, infection-induced upregulation of CXCL10, STEAP4, C3 and GFAP was significantly reduced in CK2βVas-/- mice." (PMID 40929057, 2025). "When we knocked out C3, we found that inflammatory cytokines such as TNF-α, IL-1β, IL-17A, and IL-6 were upregulated on day 1 post-infection." (PMID 40008883, 2025). "The probiotics induced the expression of immune-related genes such as IL-8, IL-1β, TNF-α, TLR-2, C3, IFN-γ, and MHC I. Additionally, these treatments increased the survival rates of grey mullet following infection with N. seriolae." (PMID 39563419, 2024). "Numerous host proteins were upregulated upon infection with Francisella, ranging from immune-related proteins to metabolic enzymes, including notably IRG1, MARCO, Rilpl2, C3, PcgF5, MT1, TRAF1, GBP2 and Fas." (PMID 38565565, 2024).